TFEB (transcription factor EB)
Diseases named in the same sentence as TFEB in open-access papers (continued):
Sharing a sentence is not in itself a finding about the gene and the disease.
viral infection (continued). "Furthermore, PAK2 KO notably mitigated the virally induced decline in TFEB protein, and endogenous TFEB ubiquitination was substantially decreased in PAK2 KO cells during viral infection." (PMID 40465712, 2025). "As our DCAF7 inhibitors demonstrated the capacity to modulate basal TFEB levels and lysosomal activity, we next sought to explore the utility of these compounds in the setting of viral infection, where the DCAF7-dependent degradation of TFEB is markedly augmented." (PMID 40465712, 2025). "Our observation that TFEB-mediated expansion and over-acidification of endo-lysosomal compartments block IAV and VSV infection opens the possibility of upregulating TFEB activity as a treatment option for reducing acid-dependent viral infections." (PMID 31919360, 2020). "Furthermore, TFEB knockdown downregulated PBLD mRNA and protein expression regardless of viral infection, whereas TFEB overexpression exerted the opposite effects." (PMID 41204829, 2026). "During dendritic cell maturation, TFEB activation enhances phagosome acidification, increases protein degradation, and improves major histocompatibility complex (MHC) class II antigen presentation, all of which are critical for initiating T cell responses against viral infections." (PMID 41450945, 2025). "In the absence of viral infection, DCAF7 KO cells demonstrated an approximately twofold increase in their TFEB protein levels compared to wild-type (WT) control cells." (PMID 40465712, 2025).
amyloid (11 papers, 2016 to 2024). "With age, decreased TFEB activity in proximal tubules causes systemic metabolic disorders and sometimes apolipoprotein A4-related amyloidosis through combined mitochondrial and lysosomal dysfunction." (PMID 39699959, 2024). "By confirming the presence of APOA4 amyloidosis, we demonstrated that the loss of TFEB in PTECs caused metabolic disorders in aged mice." (PMID 39699959, 2024). "Compared with control young patients, nuclear TFEB localization in PTECs was reduced in the elderly patient withAPOA4 amyloidosis with a genetic variant of APOA4, which we previously reported." (PMID 39699959, 2024). "TFEB downregulation in PTECs causes apolipoprotein A4 (APOA4) amyloidosis in aged mice." (PMID 39699959, 2024). "We demonstrated that TFEB deficiency in PTECs may cause APOA4 amyloidosis in aged mice." (PMID 39699959, 2024). "Supporting this result, we identified markedly decreased nuclear TFEB localization in the proximal tubules of elderly patients with APOA4 amyloidosis." (PMID 39699959, 2024). "We found that TFEB deficiency in the proximal tubules caused metabolic disorders and occasionally led to apolipoprotein A4 (APOA4) amyloidosis." (PMID 39699959, 2024). "In summary, we report that TFEB deficiency in the S3 segment of the proximal tubules of aged mice caused metabolic disorders and occasionally led to APOA4 amyloidosis." (PMID 39699959, 2024). "In APP transgenic mice specifically overexpressing TFEB in hippocampal astrocytes, TFEB mainly localizes in the nuclei of astrocytes and enhances lysosome function, resulting in reduced Aβ levels and amyloid plaque load." (PMID 36184826, 2023). "Ectopic expression of Transcription Factor EB (TFEB), the regulator of lysosomal genes, in primary astrocytes or mouse model of AD enhances lysosomal degradation of Aβ and reduces amyloid plaque load." (PMID 32708198, 2020). "Activation of TFEB in neurons is an effective strategy to attenuate Aβ generation and attenuate amyloid plaque deposition in AD." (PMID 31164812, 2019). "Furthermore, we investigated the relationship between APOA4 amyloidosis and nuclear TFEB localization in PTECs using human autopsy samples." (PMID 39699959, 2024). "Long-term loss of TFEB in PTECs did not significantly affect renal morphologic features or renal function, except for causing amyloidosis." (PMID 39699959, 2024). "Considering the results of in vivo and human autopsy samples, the age-related decrease in nuclear TFEB localization of PTECs may induce APOA4 amyloidosis in aged patients." (PMID 39699959, 2024). "TFEB is highly expressed in glial cells, thus activation of TFEB in astrocytes induces Aβ clearance and attenuates amyloid plaque, and the microglial expression of TFEB facilitates fibrillar Aβ degradation through upregulation of lysosomal biogenesis in APP/PS1 mice." (PMID 35948663, 2022). "Our findings reveal that deacetylation of TFEB could regulate lysosomal biogenesis and fAβ degradation, making microglial activation of TFEB a possible strategy for attenuating amyloid plaque deposition in AD." (PMID 27209302, 2016). "The findings in this study reveal that Resveratrol; which activates SIRT1; which in turn deacetylates TFEB, could regulate lysosomal biogenesis and fAβ degradation making microglial activation of TFEB a possible strategy for attenuating amyloid plaque deposition in AD." (PMID 34970114, 2021). "A recent study reported that TFEB accelerates lysosomal degradation of amyloid precursor protein (APP), thus reducing Aβ generation and amyloid plaque pathogenesis." (PMID 27112200, 2016). "Reduced TFEB protein may be responsible for accumulation of NFT and amyloid plaques in AD brains and deposition of a variety of mutant protein aggregates in ALS brains." (PMID 27433468, 2016). "Similarly, more recent studies demonstrated that TFEB overexpression led to marked reduction in the levels of PHF-tau and amyloid plaque burden." (PMID 27433468, 2016).
cardiomyopathy (11 papers, 2020 to 2025). A disease of the heart muscle or myocardium proper. "It has been demonstrated that defective mTOR-TFEB signaling is involved in the progression of RagCS75Y mutated cardiomyopathy, which can only be corrected by overexpression of TFEB but not inhibition of mTOR." (PMID 34490237, 2021). "TFEB overexpression could be a translatable therapeutic avenue for RagCS75Y cardiomyopathy, because adeno-associated gene transfer system has been proven safe in humans." (PMID 34071043, 2021). "For example, the autophagy-regulating transcription factor EB was activated by fasting in an animal model of HF and was shown to reverse cardiomyopathy." (PMID 38999823, 2024). "Once phosphorylated, nuclear translocation of TFEB is limited, triggering a cascade of pathological changes, such as cardiomyopathy." (PMID 37749558, 2023). "This suggests that RagD mutations identified in patients with kidney tubulopathy and cardiomyopathy impair TFEB-mediated mitophagy activation." (PMID 37188688, 2023). "In summary, the present study reveals that melatonin treatment significantly improves heart cardiac function and slows cardiac fibrosis from DOX-induced cardiomyopathy by activating the Sirt3/TFEB axis." (PMID 37760018, 2023). "A primary pathological step of RagCS75Y cardiomyopathy is defective mTOR–TFEB signaling, which can be corrected by TFEB overexpression, but not mTOR inhibition." (PMID 34071043, 2021). "There is extensive evidence for both mTOR and TFEB as therapeutic targets for cardiomyopathies of different etiology." (PMID 34071043, 2021). "In contrast, TFEB activation was sufficient to ameliorate RagCS75Y cardiomyopathy both in vitro and in vivo, suggesting a therapeutic strategy for RagCS75Y cardiomyopathy." (PMID 34071043, 2021). "Instead, TFEB activation is effective for this particular type of cardiomyopathy." (PMID 34071043, 2021). "Importantly, TFEB overexpression resulted in more nuclear TFEB and rescued cardiomyopathy phenotypes." (PMID 34071043, 2021). "Whether mTOR, TFEB, or both are effective therapeutic targets for RagCS75Y cardiomyopathy remains untested." (PMID 34071043, 2021). "Activation of the autophagy-lysosome pathway by intermittent fasting or targeted activation of transcription factor EB even at an advanced stage of disease pathogenesis was sufficient to restore normal function and rescue cardiomyopathy by restoring normal desmin localization." (PMID 32581848, 2020). "Moreover, screening of compounds that enhance TFEB nuclei translocation via directly activating TFEB or antagonizing Rags–TFEB interaction could lead to additional therapeutic avenues for RagCS75Y cardiomyopathy." (PMID 34071043, 2021). "We then tested whether TFEB could be a therapeutic target for RagCS75Y cardiomyopathy." (PMID 34071043, 2021). "In summary, we concluded that TFEB activation, but not mTOR inhibition, is therapeutic to RagCS75Y cardiomyopathy." (PMID 34071043, 2021). "Analogously, we have demonstrated that TFEB-induced upregulation of HspB8, a BAG3 partner, was essential for chaperoning desmin back to its physiologic localization state in a mouse model of R120G αB-crystallin induced cardiomyopathy." (PMID 32581848, 2020). "Therefore, mTOR inhibition failed to restore nuclear translocation of TFEB or ameliorate cardiomyopathy in RRAGC-mutant-related dilated cardiomyopathy." (PMID 37749558, 2023). "However, mTOR inhibition failed to ameliorate cardiac phenotypes in the RagCS75Y cardiomyopathy models, concomitant with a failure to promote TFEB nuclear translocation." (PMID 34071043, 2021). "For instance, rragca KO zebrafish did not exhibit cardiomyopathy-like phenotypes; the Rags complex in NRVCMs appeared activated that was supported by increased S6K/S6 phosphorylation, impaired TFEB nuclear-translocation, and decreased TFEB transcriptional activity." (PMID 34071043, 2021).
diabetic nephropathy (11 papers, 2018 to 2025). "We focused our attentions on the expression of TFEB in human diabetic kidney disease, the most prevalent cause of CKD." (PMID 29449811, 2018). "An increasing number of studies have shown that TFEB stimulates the intracellular clearance of pathogenic factors by enhancing autophagy and lysosomal function in multiple kidney diseases, such as cystinosis, acute kidney injury, and diabetic nephropathy." (PMID 32377395, 2020). "Hepatocyte growth factor regulates the PI3K/Akt-GSK3 sh-TFEB axis and protects diabetic nephropathy through the podocyte autophagy-lysosome pathway." (PMID 36707848, 2023). "Currently, in diabetic nephropathy, Smad3 was found to repress TFEB-dependent lysosome biogenesis by transcriptionally suppressing TFEB expression, resulting in autophagy dysregulation in renal epithelial tubular cells." (PMID 35327565, 2022). "This was confirmed by the findings that insufficient lysosomal replenishment and damaged lysosomal clearance coincided with TFEB inactivation, which was mediated by mTOR hyperactivation in the renal tubular epithelial cells (TECs) of diabetic nephropathy." (PMID 35082964, 2022). "It has also been reported that TFEB overexpression can suppress the impairment of autophagy in diabetic kidney disease." (PMID 33949118, 2021). "TFEB mRNA and protein levels were observed to be diminished in the kidneys of humans with diabetic kidney disease, accompanied by accumulation of the protein aggregate adaptor protein p62 in tubule epithelial cells." (PMID 29449811, 2018). "Paralleling the reduction in TFEB mRNA, TFEB protein levels in the tubulointerstitium were equivalently reduced in kidney sections from individuals with diabetic kidney disease compared to controls." (PMID 29449811, 2018). "In the present study, we discovered that expression of the transcription factor TFEB, a controller of bulk degradation, is diminished in human diabetic kidney disease and in SNx rats." (PMID 29449811, 2018). "In human diabetic kidney disease and in the kidneys of SNx rats, the increase in protein misfolding coincided with a diminution in the expression of TFEB." (PMID 29449811, 2018). "Indeed, previous studies have shown that abnormal mTORC1 hyperactivation, which leads to TFEB inactivation, is involved in the pathogenesis of tubular damage in diabetic kidney disease." (PMID 39949488, 2025). "Furthermore, both mRNA and protein expression levels of TFEB are decreased in the kidneys of patients with diabetic kidney disease, and the dysfunction of the autophagy-lysosome pathway results in the accumulation of misfolded proteins and damaged organelles." (PMID 39949488, 2025). "As disruption of lysosomal homeostasis can lead to the tubulopathy of diabetic nephropathy, we evaluated whether decreased activity of TFEB is responsible for disturbed lysosome biogenesis and clearance in this pathological process." (PMID 35082964, 2022). "Whereas TFEB mRNA and protein levels were diminished, immunostaining for p62 was increased approximately three-fold in tubule epithelial cells of kidney sections from people with diabetic kidney disease, being evident in both the cytosol and the nucleus." (PMID 29449811, 2018). "Given that trehalose activated TFEB-mediated autophagy and alleviated kidney injury in cisplatin-induced CKD mice, much more CKD models, such as UUO, diabetic nephropathy, or indoxyl sulfate-induced CKD should be applied to systematically evaluate the therapeutic effects of trehalose." (PMID 39990216, 2025).
acute kidney injury (10 papers, 2020 to 2025). Sudden and sustained deterioration of the kidney function characterized by decreased glomerular filtration rate, increased serum creatinine or oliguria. "In mice with acute kidney injury (AKI), the expression of the protein PGC-1α was diminished and overexpression of PGC-1α subsequently activated TFEB-mediated autophagy, which led to the amelioration of mitochondrial dysfunction and kidney damage." (PMID 39869517, 2025). "Meanwhile, we found that TFEB nuclear translocation and GADD45α expression levels were also inhibited in Tac-induced acute kidney injury mice (data not shown), but the role of the TFEB/GADD45α pathway in Tac-induced acute nephrotoxicity needs to be further verified." (PMID 39913188, 2025).
amyotrophic lateral sclerosis (10 papers, 2016 to 2025). Amyotrophic lateral sclerosis (ALS) is a neurodegenerative disease characterized by progressive muscular paralysis reflecting degeneration of motor neurons in the primary motor cortex, corticospinal tracts, brainstem and spinal cord. "Further supporting a link between TFEB function and healthy aging, Alzheimer’s and ALS (amyotrophic lateral sclerosis) patients have an overall decrease of nuclear TFEB." (PMID 35822019, 2021). "Therefore, pridopidine may ameliorate the TFEB transport deficit in the C9orf72 subtype of amyotrophic lateral sclerosis-frontotemporal lobar degeneration (ALS-FTD), where the mutation damages the nucleocytoplasmic transport of TFEB." (PMID 36518658, 2022). "In the C9orf72 subtype of amyotrophic lateral sclerosis-frontotemporal lobar degeneration (ALS-FTD), the hexanucleotide (G4C2)RNA expansion (HRE) disrupts the nucleocytoplasmic transport of TFEB, compromising autophagy." (PMID 35507432, 2023).
colorectal cancer (10 papers, 2019 to 2026). A primary or metastatic malignant neoplasm that affects the colon or rectum. "Recent association analysis identified a new risk locus harboring the TFEB for colorectal cancer susceptibility." (PMID 34449805, 2021). "Consistently, knockdown of TFEB in HT29 cells (a colorectal cancer cell line that has an APC mutation) resulted in reduced expression of ‘TFEB mediated Wnt target genes’." (PMID 33753903, 2021). "On the other hand, TFEB downregulation is associated with increased colorectal cancer risk and prevention of tumor-associated macrophages activation." (PMID 30979895, 2019). "On the contrary, the expression level of TFEB in colorectal cancer has been shown to be significantly low as than that in normal tissues." (PMID 33803301, 2021). "The link between TFEB-associated genes and colorectal cancer (CRC) progression and prognosis remains unclear; thus, we performed data-independent acquisition (DIA)-based quantitative proteomics to systematically identify the targets of TFEB." (PMID 36765702, 2023).
prostate carcinoma (10 papers, 2018 to 2025). A carcinoma that arises from epithelial cells of the prostate gland. "Association of TFEB expression in prostate cancer cells with clinicopathologic characteristics in 205 patients who underwent radical prostatectomy between 1993 and 1995 in Massachusetts General Hospital." (PMID 33732651, 2021). "Luteolin induces ferroptosis in prostate cancer cells by activating TFEB, affecting cell death, autophagy, and TFEB nuclear translocation, while enhancing ferritinophagy." (PMID 40916076, 2025). "Luteolin has been shown to induce ferroptosis in prostate cancer by promoting the nuclear translocation of transcription factor EB (TFEB) and enhancing ferritinophagy." (PMID 38738174, 2024). "In addition, depletion of TFEB reduces proliferation of pancreatic and prostate cancer cells, further suggesting that these transcription factors function as oncogenes." (PMID 30520728, 2018). "However, the biological role and clinical significance of TFEB in prostate cancer (PCa) remain unknown." (PMID 33732651, 2021). "Luteolin can also increase ferroptosis by regulating TFEB, increasing TFEB expression and nuclear translocation and subsequent FTH1 lysosomal degradation in prostate cancer." (PMID 39584140, 2024).
cardiac hypertrophy (9 papers, 2021 to 2025). "Furthermore, it has been reported that loss of TFEB leads to cardiac hypertrophy by blocking autophagic degradation of GATA4, a transcription factor responsible for the upregulation of several cardiac-specific fetal genes involved in cardiomyocyte growth." (PMID 37188688, 2023). "WGA staining showed that TFEB down-regulation was associated with more severe cardiac hypertrophy." (PMID 37609444, 2023). "However, if cardiomyocyte-specific targeting and overexpression of TFEB in cardiomyocytes are needed, for example, to reverse cardiac hypertrophy associated with Pompe’s disease, it may be important to further increase tissue-specific delivery." (PMID 35682624, 2022). "Furthermore, we observed that the downregulation of ASM expression increased TFEB nuclear translocation and prevented myocardial hypertrophy, an effect that was enhanced when combined with PUE treatment." (PMID 39993967, 2025). "The regulation of Beclin1-dependent autophagy by DGKζ may play a role in its impact on cardiac hypertrophy through the modulation of the mTOR/TFEB signaling pathway." (PMID 38250603, 2024). "In contrast, PIEZO1 activated calpain/calcineurin signaling to promote cardiac hypertrophy, and calcineurin could bind and dephosphorylate TFEB, thereby promoting its nuclear translocation." (PMID 37485782, 2024). "Taken together, these results suggest that the mechanisms by which DGKζ alleviates pathological cardiac hypertrophy may involve the regulation of Beclin1-mediated autophagy through the mTOR/TFEB signaling pathway." (PMID 38250603, 2024).